GPC1 (glypican 1)
Description:
Cell surface proteoglycan that bears heparan sulfate. Binds, via the heparan sulfate side chains, alpha-4 (V) collagen and participates in Schwann cell myelination (By similarity). May act as a catalyst in increasing the rate of conversion of prion protein PRPN(C) to PRNP(Sc) via associating (via the heparan sulfate side chains) with both forms of PRPN, targeting them to lipid rafts and facilitating their interaction. Required for proper skeletal muscle differentiation by sequestering FGF2 in lipid rafts preventing its binding to receptors (FGFRs) and inhibiting the FGF-mediated signaling.
Synonyms: glypican
Tractability: Antibody: its Gene Ontology location is reachable by antibodies, with high confidence; UniProt places it where antibodies can reach, with medium confidence; UniProt predicts a signal peptide or a membrane-spanning region; the Human Protein Atlas places it where antibodies can reach. PROTAC: its protein half-life has been measured.
Gene: Protein-coding gene on chromosome 2 (240,435,636 to 240,468,076, forward strand). Ensembl gene ENSG00000063660.
Subcellular location: Cell membrane; Endosome; Secreted, extracellular space (Secreted glypican-1)
Subcellular location (Human Protein Atlas): Cytosol; Plasma membrane
Pathways (Reactome):
Disease: Attachment and Entry; Defective B3GALT6 causes EDSP2 and SEMDJL1; Defective B3GAT3 causes JDSSDHD; Defective B4GALT7 causes EDS, progeroid type; Defective EXT1 causes exostoses 1, TRPS2 and CHDS; Defective EXT2 causes exostoses 2; Dengue Virus Attachment and Entry; Dengue Virus-Host Interactions; RSV-host interactions; Respiratory syncytial virus (RSV) attachment and entry
Hemostasis: Cell surface interactions at the vascular wall; Initiation of coagulation cascade; Regulation of clotting cascade
Metabolism: Glycosaminoglycan-protein linkage region biosynthesis; HS-GAG biosynthesis; HS-GAG degradation
Developmental Biology: Signaling by ROBO receptors
Sensory Perception: Retinoid metabolism and transport
Gene Ontology:
Molecular function: copper ion binding; protein binding; fibroblast growth factor binding; laminin binding
Biological process: heparan sulfate proteoglycan catabolic process; cell migration; myelin assembly; negative regulation of fibroblast growth factor receptor signaling pathway; positive regulation of skeletal muscle cell differentiation; regulation of protein localization to membrane; Schwann cell differentiation; regulation of signal transduction
Cellular component: extracellular exosome; extracellular matrix; extracellular region; membrane raft; plasma membrane; cell surface; Golgi lumen; lysosomal lumen; synapse; endosome
Genetic constraint (gnomAD): Loss-of-function variants: 24 observed, 40.1 expected, observed/expected ratio (o/e) 0.6, 90% interval 0.43 to 0.84. The upper end of that interval is the gene's LOEUF score, 0.84, which puts it in group 3 of 6, group 1 being the genes least tolerant of losing a copy. Missense variants: 762 observed, 733.15 expected, observed/expected ratio (o/e) 1.04, 90% interval 0.98 to 1.1. Synonymous variants: 377 observed, 324.49 expected, observed/expected ratio (o/e) 1.16, 90% interval 1.07 to 1.26.
Homologues: Orthologues: chimpanzee GPC1 (99% identical), macaque GPC1 (97% identical), pig GPC1 (90% identical), rat Gpc1 (89% identical), mouse Gpc1 (89% identical), dog GPC1 (88% identical), guinea pig GPC1 (88% identical), tropical clawed frog gpc1 (58% identical), zebrafish gpc1b (51% identical), zebrafish gpc1a (50% identical), Drosophila melanogaster dlp (32% identical). Paralogues in human: GPC6 (45% identical), GPC4 (41% identical), GPC2 (38% identical), GPC5 (24% identical), GPC3 (22% identical).
Diseases named in the same sentence as GPC1 in open-access papers:
GPC1 is named in the same sentence as 127 diseases in open-access papers, as found by Europe PMC text mining. Sharing a sentence is not in itself a finding about the gene and the disease. The quoted sentences say what the papers report.
pancreatic cancer (255 papers, 2005 to 2026). "This study presents a novel method for cancer immunotherapy utilizing the probiotic Escherichia coli Nissle 1917 (EcN) as an oral delivery system for Glypican-1 (GPC1), a significant tumor-associated antigen in pancreatic cancer treatment." (PMID 40282924, 2025). "Exosomes containing glypican-1 have been revealed to be a sensitive and specific diagnostic markers for pancreatic cancer." (PMID 38243280, 2024). "Further, clinical investigations show that high expression of GPC1 is associated with poor prognosis in glioblastoma, esophageal squamous cell carcinoma and pancreatic cancers." (PMID 36944188, 2023). "For example, glypican-1 (GPC-1) on cancer cell-derived EVs in serum was identified as a diagnostic index for early-stage pancreatic cancer." (PMID 37717008, 2023). "Glypican-1 (GPC1) levels in the blood have also been proposed as a possible prognostic and diagnostic biomarker for pancreatic cancer, with EV GPC1 levels being assessed in the blood." (PMID 35159299, 2022). "The levels of GPC1+ exosomes are associated with the tumor burden and patient survival after surgery, thus enabling the detection of pancreatic cancer and possibly response to therapy." (PMID 36109501, 2022). "Consistent with previous results, the expression of GPC-1 mRNA and protein was significantly increased in pancreatic cancer tissues and associated with shorter RFS of PDAC based on public databases." (PMID 36313694, 2022). "The aim of this study was to develop and establish one effective method to screen out the more specific diagnostic antibodies for pancreatic cancer GPC1 by means of flow cytometry and single-cell amplification." (PMID 34527051, 2021). "For example, exosomal GPC1 level is elevated in the serum of patients with pancreatic cancer and is associated with poor prognosis." (PMID 34301723, 2021). "Based on several reports showing proof-of-concept results for EV-associated pancreatic cancer biomarkers, GPC1 was the first candidate to enter clinical trials, aiming to evaluate its performance as a biomarker." (PMID 33494442, 2021). "The expression of GPC1 has been linked to the pathogenesis of numerous tumor entities including pancreatic cancer, esophageal squamous cell carcinoma (ESCC), and glioma." (PMID 33742285, 2021). "Although GPC1 has been used in clinical applications for the early diagnosis of pancreatic cancer, its efficacy as a diagnostic and prognostic tool is still debated." (PMID 34249755, 2021). "In additional, Glypican-1 has been widely confirmed to be up-regulated in pancreatic cancer tissues and exosomes, which can be used as a diagnostic marker for pancreatic cancer." (PMID 33169793, 2020). "Gpc-1, an exosome-associated polysaccharide protein identified in the blood, has been shown to be significantly different among healthy individuals, pancreatic cancer patients, patients with early pancreatic cancer, and those with advanced pancreatic cancer." (PMID 31467879, 2019). "GPC1+ circulating TEXs from patients with spontaneous pancreatic tumors carried specific KRAS mutation, and reliably reflected pancreatic intraepithelial lesions in spite of negative signals by magnetic resonance imaging." (PMID 31438991, 2019). "Elevated levels of glypican-1 are found in pancreas carcinoma where increased expression is associated with poor prognosis." (PMID 31620357, 2019). "They found that GPC-1 was most abundant in pancreatic cancer-associated exosomes compared to other cancer-related exosomes." (PMID 29865250, 2018). "GPC1 can serve as a potential biomarker for a noninvasive diagnostic and a screening tool for pancreatic cancer." (PMID 27673558, 2016). "GPC1 crExos from patients and from mice with spontaneous pancreatic tumours carry specific KRAS mutations and reliably detect pancreatic intraepithelial lesions in mice despite negative signals by MRI." (PMID 26316886, 2015).
pancreatic cancer (continued). "Moreover, GPC-1 expression was significantly associated with the perineural invasion of pancreatic cancer and had certain prognostic significance for pancreatic cancer patients." (PMID 38982153, 2024). "In a very interesting study, Melo and colleagues found that pancreatic cancer cell-derived exosomes were enriched with glypican-1 (GPC1) protein and could act as a potential diagnostic and screening tool to detect early stages of pancreas cancer." (PMID 38962276, 2024). "GPC1-positive EVs are diagnostic indicators of early pancreatic cancer." (PMID 36407096, 2022). "There are studies suggesting GPC1+ exosomes in combination with serum CA19-9 could serve as a diagnostic marker for pancreatic cancer." (PMID 36109501, 2022). "It has been suggested that GPC1-positive exosomal was highly expressed in the serum of pancreatic cancer patients, and the diagnostic power of the exosomal protein GPC1 (AUC = 1.0) was significantly better than CA19-9 (AUC =0.739) in distinguishing pancreatic cancer patients from healthy controls." (PMID 36119470, 2022). "Previous studies reported that glypican-1–positive circulating exosomes might be diagnostic and prognostic biomarkers for the early detection of pancreatic cancer." (PMID 33592500, 2021). "For example, Glypican-1 has been found in pancreatic carcinoma cell derived exosomes and can serve as a potential non-invasive diagnostic biomarker to facilitate the early detection of pancreatic cancer." (PMID 34434900, 2021). "In this paper, a cell surface proteoglycan (glypican-1) was identified as being specifically enriched on cancer cell-derived exosomes, serving as a potential non-invasive diagnostic and screening tool to detect the early stages of pancreatic cancer." (PMID 34898576, 2021). "However, we found that different forms of GPC1 were far more associated with exomere and supermere nanoparticles released from pancreatic cancer cells (PANC-1) and normal HRECs." (PMID 34887515, 2021). "In another study, the test of glypican-1 (GPC1) protein on cancer-cell-derived exosomes may serve as a potential diagnostic and screening tool to detect early stages of pancreatic cancer." (PMID 31249805, 2019). "Moreover, the GPC-1 expression was significantly correlated with pathologic grades and clinical stages of the pancreatic cancer, and closely associated with the poor prognosis of patients." (PMID 31355137, 2019). "Therefore, our results further support the notion that GPC1 is an attractive diagnostic and prognostic biomarker for detecting early stages of pancreatic cancer." (PMID 28440066, 2017). "Similarly, glypican-1 specifically enriched on pancreatic cancer-cell-derived exosomes was deemed as a novel diagnostic and prognostic protein." (PMID 28178689, 2017). "Glypican-1 (GPC1)-positive exosome is a diagnostic index of early stage pancreatic cancer." (PMID 28851367, 2017). "GPC1 crExos may serve as a potential non-invasive diagnostic and screening tool to detect early stages of pancreatic cancer to facilitate possible curative surgical therapy." (PMID 26316886, 2015). "The abundance of glypican-1 positively correlates with disease severity in patients, whether they have received surgical treatment or not, suggesting that glypican is a surgery-independent, inherent diagnostic biomarker of pancreatic cancer." (PMID 32825245, 2020). "In pancreatic cancer, the glypican-1 (GPC1)+ endosomes were reported as a diagnostic biomarker to distinguish healthy subjects and patients with a benign pancreatic disease from patients with early- and late-stage pancreatic cancer, with absolute specificity and sensitivity." (PMID 30104497, 2018). "Specifically, the detection of glypican-1-positive EVs has demonstrated an area under the curve (AUC) of 1.0 for identifying early-stage pancreatic cancer, significantly outperforming conventional serum markers." (PMID 41599276, 2026).
pancreatic cancer (continued). "For instance, a sole marker, Glypican-1 (GPC-1) on pancreatic cancer exosomes has been reported as a marker for detecting early-stage PC with 100% sensitivity and specificity from healthy controls." (PMID 40363817, 2025). "EVs derived from the serum of patients with pancreatic cancer showed high glypican-1 (GPC1+) levels, which correlated with the tumor burden and survival of patients before and after surgical tumor resection." (PMID 40182121, 2025). "The diagnostic value of exosomal membrane proteins is extended to tissue-specific cancer biomarkers, including glypican-1 (GPC1), which provides a high sensitivity and specificity for pancreatic cancer." (PMID 41303767, 2025). "For example, Glypican-1 (GPC-1) is utilized to detect cancer EVs and is employed for early detection of pancreatic cancer." (PMID 39816681, 2025). "While EV surface molecules like glypican-1 predict pancreatic cancer progression 38, 39 or prostate-specific membrane antigen-positive EVs correlate with breast cancer survival 40, proteins in EVs like β-catenin are less studied due to detection challenges." (PMID 40657369, 2025). "The work successfully showed the presence of GPC1 in the PANC02 pancreatic cancer cell line and assessed its impact on cellular proliferation." (PMID 40282924, 2025). "Recent studies have reported that GPC1 is highly expressed in pancreatic cancer and that GPC1 plays an important role in the neural metastasis of pancreatic cancer." (PMID 39823268, 2025). "The cell-surface proteoglycan glypican-1 (GPC1) is more abundant in exosomes produced from pancreatic cancer cells." (PMID 40305328, 2025). "In pancreatic cancer, it has been reported that regulation of GPC1 expression affects cell functions such as cell signaling, tumor growth, angiogenesis, and metastasis." (PMID 39300946, 2024). "In a study focused on pancreatic cancer, exosomes derived from CSCs were found to be enriched with Glypican-1 (GPC1)." (PMID 39200273, 2024). "GPC1 is a cell surface heparan sulfate proteoglycan that is overexpressed in different cancer types, including pancreatic cancer." (PMID 39065798, 2024). "More importantly, the levels of GPC1+ crExos correlated with the tumor burden and survival in mice and patients with pancreas cancer." (PMID 38962276, 2024). "The expression of GPC1 in pancreatic tumors and serum extracellular vesicles has also been found to be associated with poorer prognosis and higher stage and grade disease." (PMID 39598037, 2024). "Researchers also introduced a novel approach for the ultrasensitive detection of GPC1, a potential biomarker for pancreatic cancer, through a photoelectrochemical (PEC) immunosensor utilizing gold nanoclusters (AuNCs)." (PMID 39056602, 2024). "To assess the potential of EVs as biomarkers of pancreatic cancer, we investigated the relative protein expression levels of four EV biomarkers (ITGαv, ITGβ5, GPC-1, and EpCAM) in EVs isolated from PDAC cell lines, mouse models, and patient plasma." (PMID 38902362, 2024). "Serum exosomes of patients with advanced pancreatic cancer were rich in glypican-1 (GPC-1), which has good specificity and sensitivity in detecting pancreatic cancer." (PMID 38689293, 2024). "Early studies in pancreatic cancers identify correlation between GPC1 expression and TGF-β suggesting the relationship between the two molecules." (PMID 36944188, 2023). "Glypican-1 (GPC1) expression is elevated in pancreatic cancer and has been exploited as a therapeutic target." (PMID 37031249, 2023). "In pancreatic cancer, EV-specific GPC1 (glypican-1) and a miRNA signature (high miR-10b, miR-21, miR-30c, and miR-181a and low miR-let7a) can reliably detect early pancreatic cancer and have been shown to be superior to the standard CA 19-9 plasma test." (PMID 37397375, 2023). "For example, the exosomal protein GPC1 was significantly higher in serum samples from pancreatic cancer patients than in normal subjects." (PMID 37848835, 2023).
pancreatic cancer (continued). "In exosomes secreted from pancreatic cancer, overexpressed proteoglycan Glypican-1 (GPC-1) is found." (PMID 38202898, 2023). "Next, we compared the potency of D4 to that of clone 1–12 in the IgG4H-CD28TM CAR construct against low-GPC1-expressing pancreatic cancer cells." (PMID 37031249, 2023). "High expression of GPC1 is reportedly a poor prognostic factor in esophageal cancer, pancreatic cancer, cholangiocarcinoma, and glioblastoma." (PMID 37827841, 2023). "Tsujii and colleagues showed that the majority of pancreatic cancer patients express GPC1 on both the tumor and stromal cells, particularly cancer-associated fibroblasts (CAFs)." (PMID 37880707, 2023). "As a potential therapeutic target, an anti-GPC1 monoclonal antibody (GPC1 mAb) drug conjugate has been developed and has shown excellent preclinical in vivo antitumor effects in pancreatic cancer models." (PMID 37827841, 2023). "Glypican-1 is a membrane-anchored protein that is increased not only in pancreatic cancer but in other tumor tissues as well." (PMID 37760400, 2023). "Studies have shown that the GPC1 membrane protein on the surface of EV is an effective biomarker for the detection of pancreatic cancer." (PMID 37798669, 2023). "Next, we evaluated the altered GPC1 expression in pancreatic cancer by performing immunohistochemistry (IHC) with the HM2 antibody." (PMID 37031249, 2023). "To assess GPC1 levels in pancreatic cancer, we performed RT-PCR and western blot using a panel of pancreatic cancer cell lines and a normal human pancreatic duct epithelial cell line (hTERT-HPNE)." (PMID 37031249, 2023). "Studies have also shown that the human plasma exosome glypican-1 protein can be a candidate marker for the early diagnosis of pancreatic cancer." (PMID 37848835, 2023). "The exosome-derived GPC1 was enriched in pancreatic cancer patients and showed excellent ability in comparison with carbohydrate antigen (CA) 19-9 or serum-free GPC1 in pancreatic cancer screening." (PMID 36681849, 2023). "Both antibodies bound equally well to GPC1-expressing T3M4 and KLM1 pancreatic cancer cells, GPC1-overexpressing A431 cells (H8), and GPC1-overexpressing KLM1 cells (2B9)." (PMID 37031249, 2023). "Here the authors report the development of VHH nanobody-based CAR-T cells targeting GPC1, showing anti-tumor activity in pancreatic cancer preclinical models." (PMID 37031249, 2023). "Multiple studies have shown that GPC1 expression is elevated in pancreatic cancer, both in cancer cells and the adjacent fibroblasts, whereas its expression is rarely found in normal pancreas." (PMID 37031249, 2023). "Despite some controversies, we believe that exosomal glypican-1 is an early marker of pancreatic cancer that can be useful when included in a battery of tests rather than an isolated study." (PMID 37760400, 2023). "Glypican 1 (GCP1) and macrophage migration inhibitory factor (MIF) were identified as potential exosome-associated biomarkers for early diagnosis of pancreatic cancer." (PMID 36770959, 2023). "Here, we measured GPC1 antigen density on pancreatic cancer cell lines and observed low levels of GPC1 in pancreatic cancer." (PMID 37031249, 2023). "Together, D4-IgG4H-CD28TM CAR T cells demonstrate enhanced antitumor efficacy in pancreatic cancer cells with low GPC1 antigen density." (PMID 37031249, 2023). "Future studies using patient-derived xenograft models and primary tumor materials with heterogenous GPC1 expression will further validate the efficacy of D4-IgG4H-CD28TM CAR T cells in pancreatic cancer." (PMID 37031249, 2023). "Taken together, we demonstrate that D4-IgG4H-CD28TM CAR T cells are persistent and able to drive the regression of multiple low-GPC1-expressing pancreatic tumors." (PMID 37031249, 2023). "GPC1 mRNA and protein levels were appreciably higher in nearly 90% of pancreatic cancer cell lines compared with normal pancreatic duct epithelial cells." (PMID 37031249, 2023).